TRPC5 (transient receptor potential cation channel subfamily C member 5)
Diseases named in the same sentence as TRPC5 in open-access papers (continued):
Sharing a sentence is not in itself a finding about the gene and the disease.
atherosclerosis (4 papers, 2019 to 2022). A disease characterized by the build-up of fatty material and calcium deposition in the arterial wall resulting in partial or complete occlusion of the arterial lumen. "Oxidized low-density lipoprotein (ox-LDL), a risk factor accelerating atherosclerosis, was found to promote VSMCs proliferation and migration, and TRPC5 channels were sensitive to antioxidant." (PMID 32328171, 2020). "In conclusion, we demonstrate that ISL inhibits TRPC5 overexpression not only in a high-fat diet-induced atherosclerosis mouse model but also in primary VSMCs stimulated by angiotensin II." (PMID 32328171, 2020). "If there is motivation to further investigate the relationship of TRPC5 to atherosclerosis, alternative genetic approaches would be needed to circumvent the DOX limitation." (PMID 30692584, 2019). "Therefore, further studies are needed to reveal the mechanisms by which ISL modulates TRPC5 expression and inhibits atherosclerosis." (PMID 32328171, 2020). "Adiponectin is a major anti-inflammatory mediator and so we hypothesized an effect of TRPC5 on the inflammatory condition of atherosclerosis." (PMID 30692584, 2019). "Because adiponectin is a dominant anti-inflammatory mediator, we hypothesized that Ca2+ entry through TRPC5 channels might be important in inflammatory diseases such as atherosclerosis." (PMID 30692584, 2019). "Furthermore, ISL could inhibit TRPC5 expression not only in high-fat diet-induced atherosclerosis model but also in primary VSMCs stimulated by angiotensin II." (PMID 32328171, 2020). "We need to further establish atherosclerosis animal models to determine the effect of TRPC4 and TRPC5 on the proliferation of VSMCs and VECs under pathological conditions." (PMID 34899056, 2021).
cardiac hypertrophy (4 papers, 2019 to 2024). "A study using cultured neonatal rat cardiomyocytes proposed a protective role for TRPC5 against ATP-induced cardiac hypertrophy." (PMID 38672459, 2024). "We assessed the role of TRPC5 in cardiac hypertrophy by subjecting mice to aortic pressure overload through suprarenal aortic banding." (PMID 38672459, 2024). "Here, we examine the role of TRPC5 on cardiac function under basal conditions and during cardiac hypertrophy." (PMID 38672459, 2024). "The results further reveal that TRPC5 has a protective phenotype against maladaptive cardiac hypertrophy." (PMID 38672459, 2024). "The exaggerated maladaptive hypertrophy phenotype in TRPC5 KO was further supported by the increased expression profile of cardiac hypertrophy biomarkers." (PMID 38672459, 2024). "A TRPC5 and endothelial nitric oxide synthase interaction was required to produce nitric oxide and negatively regulate cardiac hypertrophy signalling." (PMID 38672459, 2024). "An exaggerated cardiac hypertrophy response to AAB was observed in TRPC5 KO mice, with an increased expression of hypertrophy markers, fibrosis, reactive oxygen species, and angiogenesis." (PMID 38672459, 2024). "Furthermore, our results reveal that TRPC5 has a protective phenotype against pressure overload-induced cardiac hypertrophy and fibrosis." (PMID 38672459, 2024). "We further proposed that TRPC5 is able to protect against pathological cardiac hypertrophy." (PMID 38672459, 2024). "Likewise, increased TRPC5 expression in human heart failure and STIM1 elevation are linked to cardiac hypertrophy." (PMID 31878108, 2019). "Nevertheless, TRPC5 is not often linked with cardiac hypertrophy or HF and more data is needed for elucidating its function in this pathology." (PMID 31315301, 2019). "Increased expression of TRPC3 and TRPC5 channels in the hypertrophied and failed hearts indicates that the TRPC channels may contribute to myocardial hypertrophy pathogenesis through calcium signaling and calcineurin/NFAT path activation." (PMID 32641948, 2019).
cholestasis (4 papers, 2017 to 2024). Impairment of the bile flow caused by obstruction within the liver, or outside the liver in the bile duct system. "Loss of TRPC5 signalling was previously suggested to attenuate liver injury caused by cholestasis and to improve kidney function in LPS-injected mice." (PMID 29983857, 2018). "Our results suggest that activation of TRPC5 contributes to the development of cholestasis and associated dyslipidemia." (PMID 28539583, 2017). "We report here a key role for TRPC5 in a murine model of cholestasis, where we show that ablation of TRPC5 was associated with an improved outcome following chronic dietary supplementation with CA." (PMID 28539583, 2017). "Therefore, our data suggest that CA-induced cholestasis is associated with hepatic dysregulation of phospholipid metabolism, giving rise to dyslipidaemia that is TRPC5 dependent." (PMID 28539583, 2017). "Collectively, the data reveals attenuated liver pathology in TRPC5 KO mice, signifying a role for TRPC5 in cholestasis-induced local liver injury." (PMID 28539583, 2017). "Elevated liver enzymes, hepatic bile acid content, inflammation and dyslipidemia were significantly attenuated in TRPC5 KO mice, suggesting that TRPC5 is positively involved in CA-induced cholestasis." (PMID 28539583, 2017). "These processes were largely blunted in TRPC5 KO mice, suggesting a detrimental role for TRPC5 in cholestasis." (PMID 28539583, 2017). "We determined that CA-induced cholestasis resulted in the typical elevated hepatic lipid profile in WT mice, which was blunted in TRPC5 KO mice." (PMID 28539583, 2017). "Overall, our results demonstrate novel findings that TRPC5 has the ability to orchestrate the development of cholestasis." (PMID 28539583, 2017). "The activation of TRPC5 is involved in the development of cholestasis and related dyslipidemia." (PMID 38255767, 2024). "The study on wild-type mice and TRPC5 knockout mice showed that TRPC5 deletion could alleviate liver dyslipidemia and liver injury induced by cholestasis." (PMID 38255767, 2024). "We investigated the contribution of TRPC5 in a murine model of cholestasis." (PMID 28539583, 2017). "The authors compared cholestasis-induced liver injury in wild-type compared to Trpc5 knockout mice, and found significantly reduced injury in knockout animals, as well as reduced dyslipidaemia and hypercholanemia, suggesting that TRPC5 channels could be involved in liver function." (PMID 29865154, 2018).
chronic kidney disease (4 papers, 2019 to 2023). Impairment of the renal function secondary to chronic kidney damage persisting for three or more months. "In addition, among the transient receptor potential (TRP) channels, short transient receptor potential channel 5 (TRPC5) has been identified as a cause of erythropoietin-induced hypertension in patients with chronic kidney disease." (PMID 37125041, 2023). "This team evaluated the benzimidazole scaffold and substituents resulting in the discovery of AC1903, a novel TRPC5 inhibitor that is active in multiple animal models of chronic kidney disease (CKD)." (PMID 32273889, 2020). "In addition to TRPC5, both gain-of-function and loss-of-function mutations in TRPC6 channel activity contribute to podocyte injury, further implicating TRPC channel activity in chronic kidney diseases." (PMID 34621762, 2021).
diabetic nephropathy (3 papers, 2019 to 2025). "A late clinical trial TRACTION-2 using GFB-887, a podocyte targeted small molecule TRPC5 inhibitor, to treat diabetic kidney disease was designed based on previous in vitro and in vivo studies showing a protective effect of TRPC5 inhibition via the Rac1 signaling pathway." (PMID 35387335, 2022). "The pyridazinone compound GFB-8438 was a highly selective, potent TRPC5 antagonist, which specifically interacted with the TRPC5-Rac1 pathway in podocytes to attenuate FSGS and diabetic nephropathy." (PMID 39860209, 2025).
dyslipidemia (3 papers, 2017 to 2025). "Finally, it would also be interesting to investigate the potential roles of TRPC members in humans, especially the involvement of TRPC4 and TRPC5 in metabolic syndrome." (PMID 40243537, 2025). "The administration of the TRPC4/TRPC5 blocker ML204 intensifies high blood glucose, dyslipidemia, fat tissue deposition, hepatic steatosis, and TNFα in HS-fed mice." (PMID 38255767, 2024).
endothelial dysfunction (3 papers, 2019 to 2025). In vascular diseases, endothelial dysfunction is a systemic pathological state of the endothelium (the inner lining of blood vessels) and can be broadly defined as an imbalance between vasodilating and vasoconstricting substances produced by (or acting on) the endothelium. "The improving effects of TRPC5 inhibition on endothelial function has potential therapeutic implications since endothelial dysfunction is involved the pathophysiology of ED, and the impairment of endothelial function has been evidenced in corpus cavernosum and penile arteries with aging and with ED." (PMID 40003900, 2025). "Plaque formation is complex and other factors such as shear stress and endothelial dysfunction might also have been affected by TRPC5 channels." (PMID 30692584, 2019).
focal segmental glomerulosclerosis (3 papers, 2024 to 2026). A renal disorder characterized by sclerotic lesions in the glomeruli. "TRPC5 is predominantly expressed in the renal system and has been linked to the pathogenesis of several renal diseases, including focal segmental glomerulosclerosis (FSGS), diabetic nephropathy, and polycystic kidney disease." (PMID 39108834, 2024). "Studies showed Rac1-activating mutations are responsible for inherited cases of focal segmental glomerulosclerosis, leading to the stimulation of TRPC5 ion channel activity and cytoskeletal remodeling in podocytes." (PMID 38384797, 2024). "Another small G protein that may be a novel target for TRPC5, Rac1, is known to mediate podocyte injury in focal segmental glomerulosclerosis." (PMID 38384797, 2024).
heart failure (3 papers, 2018 to 2019). Inability of the heart to pump blood at an adequate rate to meet tissue metabolic requirements. "TRPC5 is present in the heart and is upregulated in the cardiac myocyte hypertrophy model and human heart failure conditions." (PMID 31636563, 2019). "However, TRPC1/4/5 channels have been implicated in various human diseases, including seizures (TRPC5 and TRPC1:C4), fear-related behaviour (TRPC5), severe pulmonary arterial hypertension (TRPC4), heart failure (TRPC1/C4), and chemotherapeutic resistance of cancers (TRPC5)." (PMID 29865154, 2018).
osteoarthritis (3 papers, 2021 to 2023). A noninflammatory degenerative joint disease occurring chiefly in older persons, characterized by degeneration of the articular cartilage, hypertrophy of bone at the margins and changes in the synovial membrane. "While some osteoarthritis models suggest TRPC5 inhibition leads to more inflammation and pain, other researchers saw reversed touch pain in mice models of sickle cell disease, migraine, chemotherapy-related pain, and surgical pain after TRPC5 inhibition." (PMID 36902145, 2023). "Recently, the function of this receptor in pain perception was observed in murine models of osteoarthritis where TRPC5 KO mice had significantly exacerbated pain-like behaviors compared to that of the wild type (WT)." (PMID 36902145, 2023). "Interestingly, TRPC5 expression is reduced in human synovial samples of osteoarthritis patients, compared to health post-mortem donor." (PMID 34203675, 2021). "A third report found that deletion of TRPC5 increased mechanical sensitivity following partial meniscectomy and intraarticular injection of monoiodoacetate (MIA)—the latter of which was used to induce a model of osteoarthritis." (PMID 35760453, 2022).
rheumatoid arthritis (3 papers, 2019 to 2020). A chronic, systemic autoimmune disorder characterized by inflammation in the synovial membranes and articular surfaces. "Breaking the disulfide bridge by extracellular reduced thioredoxin (rTRX) activated TRPC5 homotetramer and TRPC5/1 heterotetramer in secretory fibroblast-like synoviocytes and suppressed synovial fluid secretion, leading to rheumatoid arthritis." (PMID 31936014, 2020). "According to research, TRP channels have become drug targets for the treatment of RA as there are multiple TRP channels in rheumatoid arthritis synovial fibroblasts, including TRPV1, TRPA1, TRPC5, TRPM3, TRPM7, and TRPM8." (PMID 30792744, 2019).
autism (2 papers, 2024). Persistent deficits in social interaction and communication and interaction as well as a markedly restricted repertoire of activity and interest as well as repetitive patterns of behavior. "We recommend that TRPC5 is included in diagnostic gene panels for severe childhood-onset obesity and for autism, which was a presenting feature in males." (PMID 38959890, 2024). "It is likely that reduced TRPC5-mediated activation of OXT neurons contributes to reduced sociability in male knockin mice and autism in boys with TRPC5 deletions." (PMID 38959890, 2024). "Intellectual disability and autism may also be present in males with larger X chromosome deletions encompassing TRPC5." (PMID 38959890, 2024).
Cognitive impairment (2 papers, 2020). Abnormal cognition is characterized by deficits in thinking, reasoning, or remembering. "The AD module associated with regulation of lipolysis in adipocytes and neuroactive ligand-receptor interaction was not preserved in healthy and mild cognitive impairment networks and the key hubs TRPC5 and BRAP identified as potential targets for therapeutic treatments of AD." (PMID 32205467, 2020).
diabetes (2 papers, 2024). "They implicate TRPC5 channels as potential targets for diagnostic and pharmacological intervention in patients with diabetes and HAAF complications." (PMID 39375537, 2024). "Therefore, we attempted to reveal commonalities between TRPC5 deficiency in mice and HAAF in diabetes patients." (PMID 39375537, 2024). "The impaired counter-regulatory adrenaline response to declining glucose levels caused by the lack of functional TRPC5 proteins resembles a pathological condition in diabetes patients called HAAF." (PMID 39375537, 2024). "Aspartic acid levels were reduced in the HAAF patients under hypoglycemia compared with the non-HAAF patients with diabetes, but were not changed under any of the conditions measured in the TRPC5-deficient animals." (PMID 39375537, 2024).
gastric cancer (2 papers, 2024). A primary or metastatic malignant neoplasm involving the stomach. "Overexpression of certain calcium ions such as TRPA1 and TRPC5 promotes chemoresistance in gastric cancer cells." (PMID 38370477, 2024).
glomerulosclerosis (2 papers, 2022 to 2025). A hardening of the kidney glomerulus caused by scarring of the blood vessels. "There are reports that TRPC5 knockout and TRPC5 inhibitors can reduce the severity of albuminuria and glomerulosclerosis in certain kidney disease models in rats and mice, suggesting that excessive TRPC5 function is pathogenic in glomeruli." (PMID 35805070, 2022). "According to the IHC results, the areas positively stained for Neutrophil gelatinase‐associated lipocalin (NGAL), TRPC5, and 8‐OHdG (an oxidative DNA damage marker) in regions with glomerular sclerosis were decreased after GQDs administration compared with that observed in the AD‐injected group." (PMID 39739624, 2025).
Hepatic steatosis (2 papers, 2023 to 2024). Steatosis is a term used to denote lipid accumulation within hepatocytes. "On the contrary, the use of TRPC4/TRPC5 inhibitors was requested for cosmetic weight loss and treatment of obesity, type II diabetes, MS, and hepatic steatosis (accession numbers: WO/2018/146485; EP3579838; US20200345741)." (PMID 37631015, 2023). "TRP channels exhibit both pro- and anti-hepatic steatosis activity, evidenced by the observation that loss of TRPC5, TRPV1, and TRPM2 protected, whereas loss of TRPV4 aggravated hepatic steatosis." (PMID 39871879, 2024).
hypercholesterolaemia (2 papers, 2019 to 2024). "The activation of TRPC6 and TRPC5 inhibits re-endothelialization of arterial injury in mice with hypercholesterolemia." (PMID 38703717, 2024).